ITPR1 (inositol 1,4,5-trisphosphate receptor type 1)
Diseases named in the same sentence as ITPR1 in open-access papers (continued):
Sharing a sentence is not in itself a finding about the gene and the disease.
glioma (5 papers, 2012 to 2023). A benign or malignant brain and spinal cord tumor that arises from glial cells (astrocytes, oligodendrocytes, ependymal cells). "Nomogram and calibration curves further confirmed that the prognostic model composed of SYT1, CREB3L3, ITPR1, RASGRF2, PDX1, and RASGRF1 has good stability and potential application value for poor prognosis in patients with glioma." (PMID 37090987, 2023). "The LASSO regression model was constructed to screen the molecular models related to glioma prognosis, which were composed of SYT1, CREB3L3, ITPR1, RASGRF2, PDX1, and RASGRF1." (PMID 37090987, 2023). "Interestingly, the imbalance of oxidative stress-related pathways was also exhibited in glioma tissues, and the expression of SYT1, CREB3L3, ITPR1, RASGRF1, RASGRF2, and PDX1 were significantly different from that of para-cancerous tissues." (PMID 37090987, 2023).
heart failure (5 papers, 2016 to 2024). Inability of the heart to pump blood at an adequate rate to meet tissue metabolic requirements. "Differential regulation of two calcium release channels (RYR2 and ITPR1) has been reported during end stage heart failure." (PMID 26537877, 2016).
osteosarcoma (5 papers, 2021 to 2022). A usually aggressive malignant bone-forming mesenchymal neoplasm, predominantly affecting adolescents and young adults. "ITPR1 works as a tumor suppressor in osteosarcoma and Sézary Syndrome." (PMID 35580861, 2022). "Thus, curcumin can act as an anti-cancer agent in osteosarcoma cells by regulating ITPR1 and increasing apoptosis." (PMID 34671398, 2021).
Alzheimer disease (4 papers, 2015 to 2023). A progressive, neurodegenerative disease characterized by loss of function and death of nerve cells in several areas of the brain leading to loss of cognitive function such as memory and language. "In the Alzheimer’s disease pathway, we found genes up-regulated (Apbb1, Atf6, Cacna1d, Calm3, Casp7, Itpr1, Lpl, and Ppp3ca) and down-regulated (Aph1b, Bid, Cycs, Fadd, Fas, and Nae1)." (PMID 28513549, 2017). "Therefore, ITPR1 could be introduced as a critical protein involved in the regulation of Ca2+ homeostasis and apoptosis in the pathogenesis of Alzheimer’s disease." (PMID 38072953, 2023). "In addition to Car8, ITPR1 function is impacted by a family of regulatory proteins including presenilin, huntingtin, DANGER, 80K-H, and cytochrome C. Mutations in two presenilin genes (PS1, PS2) account for the majority of familial early-onset Alzheimer's disease." (PMID 25734498, 2015).
ataxic cerebral palsy (4 papers, 2017 to 2024). A form of cerebral palsy caused by damage to cerebellar structures. "Two ITPR1 missense mutations (p.N587D and p.S1487D, reference sequence NM_001168272) were recognized as a cause of ataxic cerebral palsy, while an ITPR1 missense mutation (p.I2583N, reference sequence NM_001168272) was recently identified to result in severe pontine and cerebellar hypoplasia." (PMID 29186133, 2017).
Autoimmunity (4 papers, 2014 to 2022). The occurrence of an immune reaction against the organism's own cells or tissues. "Our findings support the notion that the spectrum of symptoms associated with autoimmunity to ITPR1 in neurological patients is broader than initially thought." (PMID 35907972, 2022). "The spectrum of neurological manifestations associated with ITPR1 autoimmunity is broader than initially thought." (PMID 35907972, 2022). "It is therefore of interest that a milder course of disease was associated with the exclusive presence of ITPR1-IgG/anti-Sj antibodies of the IgG2 subclass in some patients, which warrants systematic evaluation of IgG subclasses in ITPR1 autoimmunity." (PMID 35907972, 2022). "Little is known so far in terms of optimum treatment of patients with ITPR1-IgG/anti-Sj-associated autoimmunity." (PMID 35907972, 2022). "Future studies investigating the clinical associations of ITPR1-related autoimmunity should therefore include IgG subclass analyses." (PMID 27776522, 2016). "Of particular note, ITPR1 autoimmunity was associated with lung cancer in one of our patients and with multiple myeloma in another, suggesting a paraneoplastic aetiology." (PMID 27776522, 2016). "A paraneoplastic aetiology of ITPR1-IgG-associated autoimmunity in patient 1 is further suggested by the finding of ITRP1 expression in the tumour tissue in structures also stained by the patient’s IgG." (PMID 27776522, 2016). "The clinical syndromes could be associated with ITPR1‐IgG and autoimmunity to ITPR1 may underlie diseases." (PMID 34378314, 2021). "Our findings expand the spectrum of clinical syndromes associated with ITPR1-IgG and suggest that autoimmunity to ITPR1 may underlie peripheral nervous system diseases (including GBS) in some patients and may be of paraneoplastic origin in a subset of cases." (PMID 27776522, 2016). "The results from the present study suggest that the spectrum of symptoms associated with autoimmunity to ITPR1 may be broader than initially thought and may include motor, sensory (including severe pain) and autonomic symptoms compatible with (myelo)radiculopathy and/or peripheral neuropathy." (PMID 27776522, 2016). "In conclusion, our study expands the spectrum of clinical manifestations associated with anti-Sj/ITPR1-IgG and suggests that autoimmunity to ITPR1 may possibly be involved in the pathogenesis of peripheral neuropathy in selected patients, including in cases clinically suggestive of GBS." (PMID 27776522, 2016). "Further studies on anti-ITPR1 autoimmunity should therefore pay attention also to signs and symptoms of autonomic heart dysregulation and autoimmune myocarditis." (PMID 27776522, 2016). "Given this wide expression profile, it is likely that the spectrum of ITPR1 autoimmunity will broaden further as more patients are identified in the future." (PMID 27776522, 2016). "Our findings suggest a role of autoimmunity against ITPR1 in the pathogenesis of autoimmune cerebellitis and extend the panel of diagnostic markers for this disease." (PMID 25498830, 2014). "Our findings indicate a possible role of autoimmunity to ITPR1 in the pathogenesis of autoimmune encephalitis and expand the panel of diagnostic markers for this condition." (PMID 25498830, 2014). "This provides a rationale for investigating ITPR1 autoimmunity in patients with psychiatric symptoms or dementia of unknown cause as well as in patients with suspected limbic encephalitis." (PMID 35907972, 2022). "Finally, we provide evidence in favour of a paraneoplastic aetiology of ITPR1 autoimmunity by demonstrating both expression of ITPR1 by the patient’s lung tumour and binding of patient IgG to the tumour tissue." (PMID 27776522, 2016). "Whether anti-ITPR1 autoimmunity has a protective role in patients with PND, as suggested for other antibody-related syndromes such as anti-Hu, is currently unknown but warrants further investigation." (PMID 27776522, 2016).
Autoimmunity (continued). "It is still not known with certainty whether the antibody itself causes the symptoms present in patients with ITPR1 autoimmunity, since no passive transfer experiments, which would be required to demonstrate a direct pathogenic impact of ITPR1-IgG/anti-Sj, have been conducted so far." (PMID 35907972, 2022).
Intellectual disability (4 papers, 2018 to 2024). "RYR2 de novo mutations have been identified in patients with intellectual disability and activation of ITPR1 and RYR2 can lead to the release of Ca2+ from intracellular stores affecting propagating Ca2+ waves." (PMID 30148849, 2018).
autism spectrum disorder (3 papers, 2017 to 2022). A spectrum of developmental disorders that includes autism, and Asperger syndrome. "Thus, we found that Itpr1 (IP3 receptor 1), which controls calcium release from intracellular stores and is an autism spectrum disorder-associated gene, is dysregulated in CA1 pyramidal neurons of Fmr1−/y mice." (PMID 29104533, 2017).
Azoospermia (3 papers, 2023 to 2025). Absence of any measurable level of sperm,whereby spermatozoa cannot be observed even after centrifugation of the semen pellet. "One study has found that the elevated apoptosis of spermatogenic cells in non-obstructive azoospermia patients was associated with increased expression of ITPR1 and Bax." (PMID 40180900, 2025). "In this study, using gene set enrichment analysis the Inositol 1,4,5-Trisphosphate Receptor Type 1 (ITPR1) gene was identified as the sole target for hsa-miR-34b-5p, and found significantly overexpressed in non-obstructive azoospermia (NOA) patients." (PMID 38072953, 2023).
cognitive decline (3 papers, 2014 to 2025). "We include in the analysis a recent case in which ITPR1-IgG/anti-Sj was associated with progressive cognitive decline, affecting mainly short-term memory, executive dysfunction, attention deficits, a sleep disorder, and psychotic symptoms." (PMID 35907972, 2022). "In the patient described in Section A, ITPR1-IgG/anti-Sj seropositivity was associated with rapidly progressive, severe cognitive decline, mainly affecting memory, attention and executive functions; optic hallucinations; and depression." (PMID 35907972, 2022). "ITPR1-IgG/anti-Sj was associated with progressive cognitive decline in this patient, affecting mainly short-term memory, executive dysfunction, attention deficits, a sleep disorder, and psychotic symptoms." (PMID 35907972, 2022). "In addition, we provide an illustrative report on a new patient with ITPR1-IgG-associated encephalitis with cognitive decline and psychosis." (PMID 35907972, 2022). "ITPR1 is expressed in hippocampal and cortical neurons, and ITPR1 autoantibodies have been found to be involved in cognitive decline." (PMID 40696840, 2025). "Subacute dysautonomia (confirmed by thermoregulatory sweat test and autonomic reflex test) was also present in the sole previously reported patient with cognitive decline and serum ITPR1-IgG/anti-Sj antibodies." (PMID 35907972, 2022). "They provide a rationale for studies evaluating the frequency of ITPR1-IgG/anti-Sj in patients with cognitive decline and/or psychosis of unknown aetiology." (PMID 35907972, 2022). "Studies evaluating the frequency of ITPR1-IgG/anti-Sj in patients with cognitive decline and/or psychosis of unknown aetiology are warranted." (PMID 35907972, 2022).
hereditary ataxia (3 papers, 2009 to 2026). An instance of an atactic disorder that is caused by an inherited genomic modification in an individual. "Hence, ITPR1 mutant IS may help to increase our understanding of the morphological substrate underlying this type of hereditary ataxia." (PMID 25354648, 2015).
Hypertension (3 papers, 2014 to 2022). The presence of chronic increased pressure in the systemic arterial system. "Examples of ion channel-annotated genes derived from the DBP phenotype include TRPM2 (cation channel), SCN11A (sodium ion channel), ITPR1 (Ca+2-release mediator), and, (implicated in hypertension." (PMID 25519358, 2014).
lung carcinoma (3 papers, 2016 to 2022). "We first assessed associations between the expression values of all ITPRs (ITPR1, ITPR2, ITPR3) and overall survival in lung cancer patients." (PMID 35625784, 2022). "Lung cancer, haematological tumours and a paraneoplastic origin should be considered in anti-Sj/ITPR1-IgG-positive patients." (PMID 27776522, 2016). "Of note, ITPR1 has been detected at protein level only in a subset of adenocarcinomas of the lung, leaving the possibility that anti-ITPR1 seropositivity in patients may denote a subtype of adenocarcinoma in patients with lung cancer and PND." (PMID 27776522, 2016).
multiple myeloma (3 papers, 2016 to 2022). "In two cases, the disease was associated with an ITPR1-expressing adenocarcinoma of the lung and multiple myeloma, respectively." (PMID 35907972, 2022). "Here we report on serum autoantibodies to ITPR1 (up to 1:15,000) in three patients with (radiculo)polyneuropathy, which in two cases was associated with cancer (ITPR1-expressing adenocarcinoma of the lung, multiple myeloma), suggesting a paraneoplastic aetiology." (PMID 27776522, 2016). "Increased expression of ITPR1 could contribute to the efficacy of the pan-HDACi panobinostat in combination with bortezomib and dexamethasone in the treatment of relapsed or refractory multiple myeloma, which is highly sensitive to ER stress because of extensive immunoglobulin synthesis." (PMID 32264925, 2020). "Overall, a tumour was found in 9/20 (45%) of the ITPR1/anti-Sj-seropositive patients with available data (3 × breast, 1 × breast and endometrial, 3 × lung [including non-small lung cancer/adenocarcinoma in 2, not specified in 1], 1 × renal, 1 × multiple myeloma)." (PMID 35907972, 2022).
papillary thyroid carcinoma (3 papers, 2021 to 2022). "In papillary thyroid carcinoma, expression of ITPR1 was promoted via effect of lncRNA SLC26A4-AS1 mediated ETS1 recruitment, suppressing tumour growth by enhancing autophagy." (PMID 35459137, 2022). "ITPR1 was also a key candidate gene in papillary thyroid carcinoma." (PMID 35580861, 2022). "In Hu’s study, three genes (ITPR1, CCL2, and CDKN2A) were selected to predict papillary thyroid carcinoma patients’ survival." (PMID 35580861, 2022).
polyneuropathy (3 papers, 2016 to 2022). A disease or disorder affecting more than one nerve. "We also identified two different ITPR1 variants in a patient with pyramidal signs and polyneuropathy." (PMID 30778698, 2019). "Considering the high rate of paraneoplastic cases, tumour screening seems essential in patients presenting with ITPR1-IgG/anti-Sj-related autoimmune encephalitis or polyneuropathy." (PMID 35907972, 2022).
renal cell carcinoma (3 papers, 2014 to 2022). "ITPR1-mediated induction of autophagy is thought to promote renal cell carcinoma by suppressing NK cells." (PMID 35459137, 2022). "The activation of autophagy induced by ITPR1 in renal cell carcinoma results in the degradation of serine protease and impairs tumour cell killing, alleviating the disease progression." (PMID 34378314, 2021).
Anxiety (2 papers, 2022 to 2025). Intense feelings of nervousness, tension, or panic often arise in response to interpersonal stresses. "Interestingly The opioid signaling pathway revealed a small group of genes associated with fear and anxiety (ADCY9, ITPR1) which could alter fear response and be responsible for the previously observed extinction deficits." (PMID 40560842, 2025).
asthma (2 papers, 2015 to 2021). "Decreasing the activity of ITPR1 can make lung smooth muscle cells less reactive to contractile agonists to control asthma." (PMID 33791298, 2021).
autonomic neuropathy (2 papers, 2016 to 2022). An inherited or acquired peripheral neuropathy affecting the autonomic nervous system. "Studies on the frequency and syndrome specificity of anti-Sj/ITPR1-IgG in patients with PNS disorders, including, among others, GBS, autonomic neuropathies and pain syndromes of unknown aetiology, are now warranted." (PMID 27776522, 2016).
esophageal adenocarcinoma (2 papers, 2022). A malignant tumor with glandular differentiation arising predominantly from Barrett mucosa in the lower third of the esophagus. "ITPR1 was found downregulated in the esophageal adenocarcinoma (EAC) tissues compared with the normal." (PMID 35580861, 2022). "ITPR1 down‐regulation is observed in esophageal adenocarcinoma and has been recognized as a potential biomarker of prognosis in esophageal adenocarcinoma." (PMID 35611939, 2022).
head and neck carcinoma (2 papers, 2022 to 2024). A carcinoma that arises from the head and neck region. "Among the 60 DETGs, genes such as TFAP2A, CLSPN, RASEF, HIST1H3H, AKT3, and ITPR1 were associated with metastasis to secondary sites, including the lungs, and with head and neck carcinoma." (PMID 39095857, 2024).
liver cancer (2 papers, 2015 to 2022). An epithelial or non-epithelial malignant neoplasm that arises from the liver. "Studies have shown that ITPR1 is located in the endoplasmic reticulum, cytoplasm and close to the nucleus in hepatocytes and bile duct cells, and ITPR1 also plays an important role in the metabolism, proliferation and secretion of bile duct cells in liver cancer cells." (PMID 35313846, 2022).
male infertility (2 papers, 2023 to 2025). The inability of the male to effect fertilization of an ovum after a specified period of unprotected intercourse. "It has been recently reported that a gain-of-function mutation in the ITPR1 gene could result in its hyperactivation followed by male infertility in mice." (PMID 38072953, 2023). "In summary, this study for the first time provided a link between the dysregulation of the hsa-miR-34b-5p/ITPR1 axis and male infertility in humans." (PMID 38072953, 2023). "Therefore, the hsa-miR-34b-5p/ITPR1 axis could be introduced as a novel potential predictive biomarker in male infertility in humans." (PMID 38072953, 2023).
neuropathy (2 papers, 2022 to 2025). A disorder affecting the nervous system that manifests with pain, tingling, numbness, and/or muscle weakness. "We recommend that the neuropathy community consider screening undiagnosed SAN patients for ITPR1 variants, as additional cases may surface." (PMID 41325768, 2025). "The ITPR1 deletion is a possible cause of the SAN phenotype in our patient, as it has been previously associated with SCA15 with a suggestion of an associated neuropathy." (PMID 41325768, 2025). "We propose that the neuropathy community consider screening SAN patients for ITPR1 deletions, as additional cases may help clarify its clinical significance." (PMID 41325768, 2025).
pancreatic cancer (2 papers, 2015 to 2022). "Therefore, we evaluated the expression profiles and prognostic value of ITPR1-3 in pancreatic cancer through data mining." (PMID 35580861, 2022). "To evaluate the function of ITPRs on the cancer patient’s clinicopathological and survival, we investigated survival analysis of ITPR1, ITPR2, and ITPR3 for pancreatic cancer by using Kaplan-Meier Plotter and GEPIA databases." (PMID 35580861, 2022). "This study found that ITPR1 and ITPR3 were up-regulated in pancreatic cancer, while there was no significant change in ITPR2." (PMID 35580861, 2022). "The result showed that ITPR1 and ITPR3 were up-regulated in pancreatic cancer specimens than non-tumor samples, confirming the previous results." (PMID 35580861, 2022).
preeclampsia (2 papers, 2018 to 2021). Preeclampsia is a hypertensive disorder of pregnancy that is characterized by new-onset hypertension with proteinuria presenting after 20 weeks of gestation, and depending on mild or severe forms may initially present with severe headache, visual disturbances, and hyperreflexia. "Additionally, we found 2 genes, Major Histocompatibility Complex, Class II, DQ Alpha 1 (HLA-DQA1) and Inositol 1,4,5-Trisphosphate Receptor Type 1 (ITPR1) that were reported in previous studies of preeclampsia." (PMID 35719905, 2021). "Based on these findings, we cannot rule out a possible role of the MTHFR, ITPR1, and DLG2 gene variants for risk of developing preeclampsia." (PMID 29758065, 2018).
progressive ataxia (2 papers, 2020 to 2023). "Last, there were three genes (ITPR1, ATP8A2, and ATXN10) that overlapped with a gene set of hereditary progressive ataxia (n = 59) and the SN-meta-DEGs (p = 0.4320)." (PMID 33390883, 2020).
sarcopenia (2 papers, 2016 to 2025). Progressive decline in muscle mass due to aging which results in decreased functional capacity of muscles. "Our data suggest that loss of ITPR1 with age is one of the major underlying causes of sarcopenia." (PMID 27658230, 2016). "The conserved decline in ITPR1 expression in aged human skeletal muscle suggests utility as a potential therapeutic target for sarcopenia, which can be treated using ERK inhibition strategies." (PMID 27658230, 2016).